LEP (leptin)
Diseases named in the same sentence as LEP in open-access papers (continued):
Sharing a sentence is not in itself a finding about the gene and the disease.
Obesity (continued). "Some direct and indirect mechanisms by which exercise affects cancer are further discussed by Thomas, however we would like to explore those somehow connected to obesity such as energy metabolism and insulin resistance, leptin, IGF-1, chronic inflammation and obesity-related hormones and cytokines." (PMID 33371214, 2020). "Leptin levels correlate with cardiovascular dysfunction in male patients, independent of degree of obesity and hypertension." (PMID 33133017, 2020). "Furthermore, we discovered a novel beneficial effect of PAI-1 inhibitor treatment, i.e. improved leptin sensitivity, in mice with HFD-induced obesity." (PMID 32670063, 2020). "Obesity, which is common in, but not exclusive to, binge eating disorders, can disrupt normal appetite signaling regulated by leptin and ghrelin, two important hormones controlling hunger and satiety." (PMID 33153014, 2020). "Moreover, CRP can be stimulated by leptin levels and CRP seemed to bind leptin receptor exerting modulations in both adipose tissue physiology as well as pathogenesis of obesity-related diseases." (PMID 32610476, 2020). "Reddy and colleagues have reported increased ER stress markers, such as ATF6, IRE1, and CHOP, in the cortex of WNIN/ob rats, a mutant obese strain that develops spontaneous obesity with insulin and leptin resistance independent of HFD exposure." (PMID 33092099, 2020). "In our cohort, patients with a CVD event had less obesity and a numerically lower median leptin concentration than patients without a CVD event." (PMID 33276814, 2020). "We conclude that obesity and diabetes due to impaired leptin signaling contribute to pathological changes in vertebrae, as well as an immature IVD phenotype, particularly of females, suggesting a sex-dependent role of leptin in the spine." (PMID 32374776, 2020). "Obesity is related to increases in the levels of insulin, insulin-like growth factor (IGF), and adipocyte-derived factors such as tumor necrosis factor (TNF)-alpha, leptin, and interleukin (IL)-6 and a decrease in levels of adiponectin." (PMID 32466596, 2020). "However, adipocytokine secretion is strongly influenced by obesity, with higher TNF-α, IL-6 and leptin and lower adiponectin levels in adipocytes from morbidly obese subjects than from non-obese subjects." (PMID 32244787, 2020). "In obesity, dysfunctional adipocytes markedly increase the release of TNFA and leptin." (PMID 33207733, 2020). "In parallel with the reduction in body fat accumulation, other features which are typical of pregnancy with obesity, such as GDM, increased leptin and insulin resistance, stress oxidative and low-grade inflammation, are also improved by these bioactive compounds." (PMID 32630697, 2020). "In obesity, adipose tissue inflammation leads to increased secretion of proinflammatory cytokines (e.g., tumor necrosis factor alfa (TNF-α) and interleukin 6 (IL-6)) and adipokines (e.g., leptin, adiponectin, resistin, and irisin)." (PMID 33204675, 2020). "In obesity, however, a central and peripheral leptin resistance develops leading to a disruption of the negative feedback loop between adipose tissue gain and satiety." (PMID 32709161, 2020). "The positive relationships of SIRT1 with adiponectin and the negative relationship with leptin were congruent with both fat amount and distribution in all the categories of fat abundance tested, from AN through NW to obesity." (PMID 33202604, 2020). "For instance, mixed nuts supplementation decreases leptin concentrations in overweight individuals, but not a walnut-rich meal in healthy individuals or a 48 g walnut smoothie in patients with obesity." (PMID 31940832, 2020). "RPTPε-null mice are leptin-sensitive and protected from HFD-induced obesity." (PMID 32731387, 2020). "First, additional systemic blood testsrelated to obesity, including leptin and adiponectin, were not included in theanalysis and should be performed in future studies for a more comprehensiveassessment." (PMID 33084815, 2020).
Obesity (continued). "In obesity, the adipocyte is dysfunctional with excessive production and secretion of pro-inflammatory adipokines, such as tumor necrosis factor α (TNF-α), interleukin 6 (IL-6), and leptin." (PMID 33597945, 2020). "Leptin was negatively correlated with Clostridium, Bacteroides and Prevotella, and positively correlated with Bifidobacterium and Lactobacillus.The results of the studies on the relationship between GSD, obesity, and incretin hormones remain controversial." (PMID 33375615, 2020). "The remaining 5 mice with RYGB completely resisted diet-induced obesity, as their body weight, fat mass, adiposity index after 30 weeks, and plasma leptin levels after 13 weeks were not significantly different compared to the non-surgical chow controls." (PMID 31133715, 2019). "Truncated non-functional leptin-expressing ob/ob mice and inactive leptin receptor-expressing db/db mice present with hyperphagia and obesity immediately after ablactation." (PMID 31805752, 2019). "Molecular docking analysis of twenty two phytoconstituents from Hibiscus rosa-sinensis, against seven targets of obesity like pancreatic lipase, fat and obesity protein (FTO protein), cannabinoid receptor, hormones as ghrelin, leptin and protein as SCH1 and MCH1 is detailed in this data article." (PMID 31193691, 2019). "There also has been no general agreement on how obesity affects the function of leptin and kisspeptin upon the reproductive axis." (PMID 31871451, 2019). "In conclusion, the high-unsaturated fat diet-induced obesity improved the vascular reactivity to leptin and does not generate endothelial dysfunction, possibly by the increase in the vascular sensitivity to leptin and increasing NO bioavailability." (PMID 30949067, 2019). "Our findings suggest an importance of leptin in evaluating obesity by the waist circumference of children which does not appear when considering BMI percentile." (PMID 31236292, 2019). "In mice lacking leptin (ob/ob) or leptin receptors (db/db), a voracious appetite elicited by high AgRP/NPY activity is associated by marked obesity and type 2 diabetes." (PMID 31620009, 2019). "Due to single gene mutations that lead to the lack of action by the satiety factor leptin or its cognate receptor, these rodents spontaneously develop severe hyperphagia leading to obesity and manifest some characteristics of type 2 diabetes mellitus." (PMID 30871282, 2019). "Friedman alone directed several key follow-up studies, including the demonstration that replacing the ob gene product leptin in ob/ob mice lacking it corrected their obesity." (PMID 30357355, 2019). "With regard to adiponectin and leptin, two critical mediators of metabolic homeostasis in adipose tissue and possible regulators of CD4+ T cell function, leptin treatment increased IFN-γ+ CD4+ T cell frequencies in NCD mice and slightly reduced Th1 and Th17 frequencies during obesity." (PMID 31736971, 2019). "The results in our study were consistent with recent findings that leptin, but not insulin, mediated the SNS-driven increase in heart rate and blood pressure associated with obesity." (PMID 31682617, 2019). "A voxel-based morphometric study showed a reduced volume of the putamen in obesity and a negative correlation between fasting plasma leptin concentrations and obesity, suggesting leptin mediated role of the putamen in regulating food intake." (PMID 30881281, 2019). "In the case of adiponectin (Acrp30), it has been found that their levels are low in psoriasis in correlation with obesity, but not in the case of leptin and resistin, which correlate with their exacerbation." (PMID 31275060, 2019). "During the development of obesity, pre-adipocytes differentiate incorrectly, and the generation of hypoxia-inducible factor-1 (HIF-1) is induced by hypoxia to increase the expression of leptin and inhibit the expression of adiponectin." (PMID 31500658, 2019).
Obesity (continued). "While ghrelin was increased and leptin was reduced, a decreased body weight and no signs of metabolic syndrome or obesity were found in this model." (PMID 30804011, 2019). "Additionally, the excessive fat in obesity, especially visceral fat, produces cytokines including MCP-1, IL-6, and TNF-α, and adipokines such as leptin, which regulate pro-inflammatory cytokines." (PMID 31123488, 2019). "It is interesting that we identified leptin as a top-ranking factor for obesity defined by waist circumference, but not for obesity defined by BMI." (PMID 31236292, 2019). "Our results showed that CXCL12 rs501120, LEP rs7799039, and FTO rs9939609 polymorphisms were associated with T2D in subjects with obesity, but not in subjects without obesity." (PMID 30764545, 2019). "Upon stratification of aPCOS group by obesity status, we found the obese aPCOS group to have a significantly lower adiponectin, A:L, and A:R but higher leptin and L:R compared to the non-obese aPCOS and ovulatory group, respectively." (PMID 31416473, 2019). "Obesity alters ASCs to acquire tumorigenic characteristics, which are then recruited to the tumor microenvironment and secrete increased levels of leptin, resulting in enhanced metastasis of TNBC through leptin-mediated pathways." (PMID 31118047, 2019). "Clearly, chronic pain is fraught frequently with obesity, but not in general; hence leptin and relatives should be integrated into chronic pain assessment on the other hand as LP drives IL-1 synthesis, which in turn promotes a chronic pain state." (PMID 31554241, 2019). "Loss of TG2 did not affect the obesity-related alterations in the expression levels of the adiponectin and resistin, but obesity-induced expressions of TNF-α, MCP-1, and leptin were significantly enhanced in the gWAT adipocytes of TG2 null animals as compared to wild type mice." (PMID 31165747, 2019). "When the population was classified by sexual development, both children (pre-pubertal stage) and adolescents (pubertal stage) with obesity showed higher body weight, height, BMI, waist circumference, HOMA index, and plasma insulin, and leptin than those with normal weight." (PMID 31207920, 2019). "Some studies report comparable adiponectin, leptin and resistin levels in PCOS whiles others report lower adiponectin, higher leptin and resistin levels among women with PCOS than controls in relation to obesity." (PMID 31416473, 2019). "Unlike leptin signaling in the hypothalamus, that in the gut is independent of the obesity development." (PMID 31141984, 2019). "Within human literature, there is growing evidence that leptin is not merely a marker of obesity, but an important pro-inflammatory adipokine involved in the pathophysiology of metabolically induced cardiovascular and renal disease." (PMID 30808423, 2019). "As an anti-obesity hormone, leptin was observed to be increased in obesity irrespective of T2D status." (PMID 31396158, 2019). "In this mouse model of predisposition to obesity and DT2 on account of an Ob mutation of leptin rendering the latter non-functional, IL233 treatment during or after the appearance of DT2 provides protection from diabetic nephropathy." (PMID 31507607, 2019). "Although the initial and quite reasonable hope was that leptin would become as dramatic a treatment of obesity as insulin was for diabetes, this has not proven to be the case." (PMID 30357355, 2019). "Due its lack of functional leptin, the ob/ob mice present hyperphagia, which contributes to obesity, insulin resistance, and type 2 diabetes development." (PMID 31866872, 2019). "Furthermore, CCK in a stabilized form resistant to degradation in the GI tract is effective at reducing food intake and body weight in DIO rodents, and activating CCKA receptors enhances the anti-obesity properties of GLP-1 agonists, amylin, and leptin." (PMID 31281260, 2019).
Obesity (continued). "The inability of leptin to exert its anorexigenic effects in obese individuals, and therefore, the lack of clinical utility of leptin in obesity, is defined as leptin resistance." (PMID 31717265, 2019). "Although leptin resistance in the brain has an essential role in obesity, the effect of E. cava extract on leptin resistance has not been revealed." (PMID 31600939, 2019). "Moreover, obesity-related anthropometric traits (i.e., BMI, waist circumference, and FAT %) and leptin were increased gradually from normal weight to overweight and obese groups (all P < 0.001)." (PMID 31285522, 2019). "Tissue-specific deletion of OB-RB in rodent neurons, but not hepatocytes, results in obesity, indicating that the regulatory effects of leptin signaling on adipose mass are mediated centrally." (PMID 31110923, 2019). "It is reported that HFD could gradually lead to elevation of serum leptin level and central leptin resistance that affected food intake differently in three stages of HFD-induced obesity development in c57 mice." (PMID 31847305, 2019). "SOCS3 upregulation and altered systemic leptin levels could be responsible for the reduced type I IFN response as well as other immune dysfunction relevant to T cells and B cells in people with obesity." (PMID 31726661, 2019). "We found that adiponectin, which is decreased during inflammation-induced by obesity, was significantly decreased in infected animals (p = 0.0186), whereas, we found no change in the amount of leptin, which is positively correlated with body weight." (PMID 31220189, 2019). "In 1994, the fat mass regulating hormone leptin was identified, but unfortunately, leptin was not successful as a treatment of common obesity in humans." (PMID 30888399, 2019). "Leptin was initially described as an anti-obesity hormone, acting through a negative feedback loop between adipose tissue and the hypothalamus to control energy homeostasis." (PMID 30949073, 2019). "Most importantly, the one large study of leptin therapy for human obesity, conducted by Amgen, failed to achieve its therapeutic endpoint for efficacy in an unselected population with obesity." (PMID 30357355, 2019). "Although leptin levels in obesity are usually high, a lack of satiation is observed indicating a state of leptin resistance." (PMID 31533725, 2019). "To assess the metabolic consequences of maternal diet-induced obesity in the offspring, we first determined body weight gain and non-fasted insulin and leptin levels of the dams." (PMID 31572115, 2019). "Lack of LEP‐mediated signaling (mutation in LEP or LEPR) leads to the increased tendency of food uptake, severe obesity, hypothyroidism, and infertility." (PMID 31070016, 2019). "Future work will be required for a better understanding of the effects of leptin in hematopoietic regulation both cell- and non-cell-autonomously, especially in obesity where leptin production by adipocytes is increased." (PMID 31109063, 2019). "Because hyperleptinemic obese individuals are much less obese than those completely lacking leptin or its receptor, it is evident that elevated leptin levels in typical obesity do continue to mediate leptin action on energy balance pathways." (PMID 30357355, 2019). "Prominently, leptin also fails to improve diabetes and insulin resistance in type 2 diabetic patients comorbid with obesity." (PMID 31718027, 2019). "A further understanding of leptin and insulin signaling within the hypothalamic ARC and the contribution of epigenetic mechanisms to the onset of obesity and related complications could aid in the development of novel antiobesity strategies." (PMID 31660128, 2019). "Obesity, accompanied by increases in basal insulin and leptin, decreases rather than increases spontaneous energy expenditure through physical activity." (PMID 30678194, 2019).
Obesity (continued). "However, pathological states such as obesity have been related to peripheral leptin resistance development, and dietary components have been proposed to modulate leptin actions in these peripheral tissues, suggesting that leptin resistance may also result from specific nutrient intake." (PMID 30441779, 2018). "Modulating leptin sensitivity, rather than leptin levels, is then an emerging frontier for obesity therapy and prevention." (PMID 29379096, 2018). "However, leptin's tight relationship with other key players in OSA, including obesity and insulin sensitivity, especially in T2D individuals, make it difficult to draw specific conclusions about the role of leptin in OSA." (PMID 30127766, 2018). "The present work is the first, to our knowledge, to demonstrate that the absence of pineal Mel leads to leptin resistance—the basis of obesity." (PMID 29636725, 2018). "The increased amount of WAT in obesity may attribute to the increased circulating concentrations of TG, FFA, insulin, and leptin." (PMID 30558262, 2018). "Therefore, COSCs can ameliorate leptin resistance via upregulating LepRb and activating the JAK2-STAT3 signaling pathway, contributing to the improvement of obesity." (PMID 29874843, 2018). "We investigated effects of obesity and short-term intake of soy protein with isoflavones (SPI) on body weight change, energy intake, liver steatosis, and serum aspartate aminotransferase (AST), alanine aminotransferase (ALT), and leptin levels." (PMID 29757972, 2018). "Serum cytokine concentrations were not altered either by diet‐induced obesity or by T3 treatment, except for leptin levels which were increased both in the obese nontreated and T3‐treated rats." (PMID 29388360, 2018). "Previous reports have shown that running wheel activity or voluntary exercise prevents hyperphagia and obesity in various animal models of obesity, but such effects seem only minimal in obese animals lacking leptin or leptin receptors." (PMID 29896090, 2018). "Obese mice have higher plasma levels of leptin than WT counterparts, but similar levels of leptin in the CSF, suggesting that leptin transport, while not diminished by obesity, does not increase with higher plasma concentrations of leptin." (PMID 30618559, 2018). "When stratifying by BMI, leptin levels showed no significant change in normal weight and individuals with obesity." (PMID 30618796, 2018). "The meta-analysis results regarding metabolic and obesity markers indicated that triglycerides, total cholesterol, CRP, BMI, total body fat percentage, waist circumference, waist–hip ratio, systolic BP, and leptin levels were positively correlated with chemerin levels." (PMID 29720894, 2018). "Two variants in the leptin gene (rs2167270 and rs4731426) were associated with increased CRC risk in women but not in men, and were not concomitantly associated with obesity." (PMID 30379922, 2018). "Leptin resistance was suggested as mechanistic explanation of increased circulating leptin in obesity and T2D compared to non-obese/non-diabetic individuals, and similar variability was seen in this study." (PMID 29596446, 2018). "The fact that body weight and adiposity are unaltered in adult (P70) Nnat null mice suggests that the defective leptin sensitivity observed in these mice is a primary defect, rather than being secondary to the development of obesity." (PMID 30279096, 2018). "Studies have also shown that there is an increased inflammatory response related with the presence of hyperleptinemia without obesity, and that leptin is able to control TNF-α production and activation by macrophages." (PMID 29189992, 2018). "Since obesity is a common feature in PCOS, it is expected that women with PCOS may exhibit an impaired status of different adipokines including leptin." (PMID 30510663, 2018). "Oxidative stress in testicular tissue, and a high level of leptin, may provide some evidence to clarify the mechanisms of male SH with DEHP and obesity." (PMID 29887939, 2018).